AS3MT (arsenite methyltransferase)
Diseases named in the same sentence as AS3MT in open-access papers:
AS3MT is named in the same sentence as 30 diseases in open-access papers, as found by Europe PMC text mining. Sharing a sentence is not in itself a finding about the gene and the disease. The quoted sentences say what the papers report.
schizophrenia (18 papers, 2016 to 2025). A major psychotic disorder characterized by abnormalities in the perception or expression of reality. "Research has shown that AS3MT is implicated in normal neurodevelopment and neurodevelopmental disorders such as schizophrenia." (PMID 39535371, 2025). "Further, evidence supports the role of AS3MT splice variants in neuropsychiatric disorders as AS3MTd2d3 shows increased expression in schizophrenia patients versus controls." (PMID 35719055, 2022). "Of note, AS3MT was found to be associated with schizophrenia in a transcriptome‐wide association study." (PMID 35719055, 2022). "A genomic region on chromosome 10q24 has been consistently associated with schizophrenia with risk attributed to the AS3MT gene." (PMID 35719055, 2022). "In this study, we used CRISPR‐Cas9 gene editing to KO and functionally characterize the schizophrenia‐associated gene AS3MT in a neuronal‐like cell line." (PMID 35719055, 2022). "The rationale for interrogating the VNTR was its high potential to be a schizophrenia-causative variant within the AS3MT gene." (PMID 36293479, 2022). "AS3MT gene is associated with various diseases including Borst-Jadassohn intraepidermal carcinoma of dermal system, liver injury, schizophrenia, and attention deficit or hyperactivity disorder." (PMID 34899152, 2021). "The Arsenic (+3 oxidation state) methyltransferase (AS3MT) gene has been identified as a top risk gene for schizophrenia in several large-scale genome-wide association studies." (PMID 32308175, 2021). "Taken together, AS3MT is clearly implicated in both normal neurodevelopment and neurodevelopmental disorders such as schizophrenia and its VNTR is the functional polymorphism." (PMID 32308175, 2021). "Rs7085104 upstream of AS3MT gene, a top GWAS-identified SNP associated with schizophrenia, is linked with a variable number tandem repeat sequence in exon 1 of AS3MT that is involved in the expression of the arsenite methyltransferase isoform (AS3MTd2d3)." (PMID 32271837, 2020). "A different SNP (rs7085104) at this locus is associated with schizophrenia, and has been shown to act through the up-regulation of a human-specific truncated isoform of AS3MT which is expressed in neurons and astrocytes." (PMID 28957430, 2017). "Together, our results provide novel insights into the potential role of AS3MT in brain development and identify pathways through which genetic variation in this region may confer risk for schizophrenia." (PMID 35719055, 2022). "The lead schizophrenia‐associated risk variant (rs11191419) is associated with altered expression of AS3MT in whole fetal brain and adult hippocampus and caudate, and another SNP in the region (rs7085104) is associated with differential isoform expression of AS3MT." (PMID 35719055, 2022). "Although the function of this enzyme in the zebrafish brain is unknown, polymorphisms in the human orthologue, AS3MT, have been linked to schizophrenia and altered brain activation during a memory task indicating a role in neural plasticity." (PMID 35501893, 2022). "AS3MT gene was associated with schizophrenia and attention deficit or hyperactivity disorder." (PMID 34899152, 2021). "Notably, AS3MT rs7085104 as a schizophrenia-associated risk SNP altered striatal dopamine synthesis capacity." (PMID 34899152, 2021). "Additionally, we have identified eight chromatin peaks with a high probability of shared causal cQTL variant with schizophrenia GWAS variants, one of these peaks also shares genetic effects with an eQTL affecting the expression of AS3MT and WBP1L in DLPFC." (PMID 30087329, 2018). "Although this locus encompasses 13 protein‐coding genes, follow‐up studies have nominated AS3MT as the lead candidate for a role in schizophrenia." (PMID 35719055, 2022). "We also identified expression changes in key genes previously associated with schizophrenia such as ZNF804A and DRD2, indicating that AS3MT is a key regulator of both these genes." (PMID 35719055, 2022).
schizophrenia (continued). "We have successfully created a knockout of the schizophrenia candidate gene AS3MT in the SH‐SY5Y neuronal cell line." (PMID 35719055, 2022). "We found that a few genes identified by MSG had been reported to influence schizophrenia risk via splicing (Note 1 Section 1C in S1 Appendix), including SNX19, AS3MT, and CYP2D6." (PMID 35771864, 2022). "Our results show an enrichment of the dysregulation of genes involved in schizophrenia, neuronal development, and cellular adhesion following knockout of AS3MT." (PMID 35719055, 2022). "We observed that only the cQTL located in the AS3MT gene colocalized with eQTLs (eQTLs of both AS3MT and WBP1L), indicating that a single genetic variant can affect the expression level of multiple genes at schizophrenia GWAS loci." (PMID 30087329, 2018). "Two separate cQTLs in MAD1L1 (PP(H4) > 0.98), one cQTL in AS3MT (PP(H4) = 0.98), one cQTL in TSNARE1 (PP(H4) = 0.94), and one cQTL in RERE (PP(H4) = 0.92) were found to colocalize with schizophrenia-associated variants." (PMID 30087329, 2018). "Largest and most consistent effects were observed on BORCS7, AS3MT, and NT5C2, providing functional support for these as genuine susceptibility genes for schizophrenia." (PMID 27004590, 2016). "We report altered cis‐regulation of BORCS7, AS3MT, and NT5C2 in association with schizophrenia risk variation, implicating these as genuine schizophrenia susceptibility genes at the locus." (PMID 27004590, 2016). "While not excluding effects on other genes in the region, this study implicates altered neural expression of BORCS7, AS3MT, and NT5C2 in susceptibility to schizophrenia arising from genetic variation at the chromosome 10q24 locus." (PMID 27004590, 2016). "Moreover, genome-wide association studies (GWASs) also supported the importance of AS3MT in the etiology of neurodevelopmental disorders such as schizophrenia." (PMID 32308175, 2021). "Moreover, AS3MT expression is highly expressed in adult human neurons and astrocytes during human stem cell differentiation toward neuronal fates and in brains of patients with schizophrenia compared with controls." (PMID 34899152, 2021). "A meta-analysis of 18 GWASs for schizophrenia supported involvement of the MHC region, TCF4, POM121L2, NOTCH4, AS3MT, CNNM2, and NT5C2." (PMID 27064909, 2016). "Meanwhile, based on our results, AS3MT, SFXN2, and PCCB may be potential biomarkers for preventing breast and thyroid cancers in patients diagnosed with schizophrenia." (PMID 36138824, 2022).
breast carcinoma (3 papers, 2016 to 2026). "In conclusion, AS3MT protein expression was higher in breast cancer tissues than in normal breast tissues, and SFXN2 protein expression was higher in thyroid cancer tissues than in normal tissue." (PMID 36138824, 2022). "AS3MT mRNA expression is closely related to the incidence of breast cancer." (PMID 36138824, 2022). "Using TCGA gene expression data, we found that the AS3MT and PCCB genes were differentially expressed in breast cancer, and the expressions of SFXN2 and PCCB were significantly different in ovarian cancer." (PMID 36138824, 2022). "We identified that AS3MT and SFXN2 might be employed as biomarkers in the future to help SCZ patients avoid breast cancer and thyroid cancer." (PMID 36138824, 2022).
atherosclerosis (2 papers, 2018 to 2023). A disease characterized by the build-up of fatty material and calcium deposition in the arterial wall resulting in partial or complete occlusion of the arterial lumen. "Exposure of apoE−/−/As3mt−/− double-knockout mice to different arsenicals suggested that AS3MT function is directly correlated with the risk of atherosclerosis." (PMID 35362847, 2023). "The AS3MT SNPs that correlate with enzyme function could predict the risk of developing atherosclerosis in arsenic-exposed populations." (PMID 35362847, 2023). "We investigated the effect of candidate variants in AS3MT (arsenic (III) methyltransferase) with urinary arsenic metabolites and their principal components in a subset of 264 participants in the Multi-Ethnic Study of Atherosclerosis (MESA)." (PMID 29874848, 2018).
bladder cancer (2 papers, 2022 to 2024). "Furthermore, individuals with genetic polymorphisms (e.g., in AS3MT enzyme) have also been linked to increased risks of arsenic-induced malignancies, including lung and bladder cancers." (PMID 39717738, 2024).
lung carcinoma (2 papers, 2024). "CHAF1A, CEP192, and AS3MT were reported to be associated with tumor progression involved with several tumors, such as hepatocellular carcinoma and lung cancer Further explorations are needed to investigate the biological mechanisms of these 6 shared genes on IS and obesity." (PMID 39734234, 2024). "Importantly, there is some evidence demonstrating an association between arsenite methyltransferase (AS3MT, an enzyme involved in arsenic metabolism catalyzing the methylation of arsenic) polymorphism, and arsenic-related cancer risk, including lung cancer." (PMID 39717738, 2024).
anemia (1 paper, 2023). A reduction in the number of red blood cells, the amount of hemoglobin, and/or the volume of packed red blood cells. "We found that AsIII exposure resulted in the development of anemia in an As3MT-dependent manner." (PMID 36936034, 2023).
epilepsy (1 paper, 2021). A brain disorder characterized by episodes of abnormally increased neuronal discharge resulting in transient episodes of sensory or motor neurological dysfunction, or psychic dysfunction. "In this study, we investigated the association of AS3MT gene polymorphism with susceptibility to epilepsy in children from south China." (PMID 34899152, 2021). "Our study revealed that genetic polymorphism of AS3MT rs7085104 was associated with the susceptibility to pediatric epilepsy and risk of AEDs-related dADRs." (PMID 34899152, 2021). "The findings of our study showed that frequency distribution of AS3MT rs7085104 genotypes was associated with pediatric epilepsy in a Han Chinese population from Southern China." (PMID 34899152, 2021). "Therefore, exploring AS3MT gene polymorphism will provide information on understanding susceptibility to pediatric epilepsy and drug safety." (PMID 34899152, 2021). "Hence, analysis of AS3MT polymorphisms will help to evaluate susceptibility to pediatric epilepsy and drug safety." (PMID 34899152, 2021). "AS3MT may be a novel potential gene implicated in pathogenesis of epilepsies." (PMID 34899152, 2021). "Whether genetic polymorphism of AS3MT contributes to epilepsy remains unclear." (PMID 34899152, 2021). "Target pathway/function network of AS3MT in epilepsy was explored through bioinformatic analysis to predict underlying mechanisms." (PMID 34899152, 2021). "Bioinformatics analysis revealed that the effects of AS3MT on epilepsy likely involved multiple targets including MTHFR, GSTM1, CYP17A1, NT5C2, YBX3, CNNM2, CACNB2, and TRIM26." (PMID 34899152, 2021). "The effects of AS3MT on epilepsy might involve multiple targets including CNNM2, CACNB2, TRIM26, MTHFR, GSTM1, CYP17A1, NT5C2, and YBX3." (PMID 34899152, 2021). "Potential mechanisms of AS3MT in epilepsy were further explored through bioinformatics analysis." (PMID 34899152, 2021). "Therefore, we deduce that AS3MT may exert its effect on epilepsy and VPA-induced dADRs through these genes." (PMID 34899152, 2021). "However, studies have not explored the role of the gene mutation of AS3MT in epilepsy." (PMID 34899152, 2021). "In addition, gene polymorphism may possibly alter gene transcription, therefore, AS3MT mRNA and protein expression in different genotypes of AS3MT rs7085104 should be determined to provide insights into the molecular mechanisms of AS3MT in pediatric epilepsy and drug safety." (PMID 34899152, 2021).
glioma (1 paper, 2024). A benign or malignant brain and spinal cord tumor that arises from glial cells (astrocytes, oligodendrocytes, ependymal cells). "The results indicated that AMT, AS3MT, EGFR, NICN1, and POLR3K exhibited significant sex differences in expression within glioma tissues." (PMID 39722126, 2024).
Insulin resistance (1 paper, 2022). Increased resistance towards insulin, that is, diminished effectiveness of insulin in reducing blood glucose levels. "Together, these findings suggest that AS3MT-promoted and METTL14-dependent RNA m6A modification plays a critical role in arsenic-exposure-caused NLRP3 inflammasome activation and subsequent hepatic insulin resistance." (PMID 36233132, 2022). "It was also found that the arsenite methyltransferase (AS3MT) interacts with and activates the NLRP3 inflammasome during arsenic-induced hepatic insulin resistance." (PMID 36233132, 2022).
liver fibrosis (1 paper, 2018). "Notably, AS3MT, GSH and TGF-β1 which were considered associated with liver fibrosis were significant up-regulated under high dose sodium arsenic exposure." (PMID 29459688, 2018).
migraine (1 paper, 2017). "Two have previously been identified as cross-phenotype loci between migraine and CAD (locus 1 in PHACTR1 and locus 3 in AS3MT), while one (locus 2, in KCNK5) is new." (PMID 28957430, 2017).
neuroblastoma (1 paper, 2022). Neuroblastoma (NB) is the most common solid, extracranial childhood tumor. "In this study, we used CRISPR/Cas9 to knockout AS3MT in the human SH‐SY5Y neuroblastoma cell line to investigate the role of AS3MT in neuronal cell function and explore its effect on cell morphology, AS3MT isoform usage, and the transcriptomic regulation of other genes in a cancer model." (PMID 35719055, 2022).
Obesity (1 paper, 2024). Accumulation of substantial excess body fat. "Several potential functional genes, including CHAF1A, CEP192, ULK4, CYP2D6, AS3MT, and WARS2, were identified as common genetic factors linking obesity and IS." (PMID 39734234, 2024). "The identification of CHAF1A, CEP192, ULK4, CYP2D6, AS3MT, and WARS2 as potential functional genes common to both obesity and IS enriched our understanding of their genetic interplay, potentially advanced our grasp of their pathogenesis and therapeutic targets." (PMID 39734234, 2024).
sarcopenia (1 paper, 2025). Progressive decline in muscle mass due to aging which results in decreased functional capacity of muscles. "The over‐expression of nine genes (MMP24‐AS1, HLA‐DRB6, HLA‐DQA2, DDX42, BAG6, NUSAP1, LINC00940, NME1‐NME2 and AS3MT) in the amygdala region showing detrimental effect on all the five sarcopenia‐related traits, whereas three genes (HLA‐DRB1, HLA‐DQB1‐AS1 and C6ORF3) showing protective effect." (PMID 39535371, 2025). "Although the role of these genes in sarcopenia and muscle function has not been studied, some of them such as AS3MT and EDEM2 have been reported to affect brain function and development." (PMID 39535371, 2025).
Stroke (1 paper, 2015). Sudden impairment of blood flow to a part of the brain due to occlusion or rupture of an artery to the brain. "Other SNPs in genes involved in inflammation (APOE and IL6), oxidative stress (NOS3 and SOD2), and As metabolism (AS3MT, CBS, GSTO1, and MTHFR) showed nominally significant interactions with well-water As for associations with CVD, CHD, or stroke." (PMID 25575156, 2015).
thyroid cancer (1 paper, 2022). "In breast and thyroid cancer, genes corresponding to the intersection sites (rs11191419, rs13240464, rs7432375) included SFXN2, AS3MT, IMMP2L, and PCCB." (PMID 36138824, 2022).
cancer (8 papers, 2018 to 2026). A tumor composed of atypical neoplastic, often pleomorphic cells that invade other tissues. "Current studies suggest that arsenite methyltransferase (AS3MT), the main factor mediating the methylation process, may lead to depletion of S‐adenosine and hypomethylation of the entire DNA, causing abnormal gene expression in cells and predisposes to cancer." (PMID 39189802, 2024). "Both AS3MT and MiR-548c-3p may be highly involved in metabolizing arsenic, activating cancer and inducing toxicity, but they may play their roles in different ways." (PMID 30543710, 2018). "Arsenic can promote cancer through epigenetic mechanisms, and AS3MT plays a role in this process." (PMID 30543710, 2018). "AS3MT and MiR-548-3p may play roles in arsenic metabolism, promoting cancer and inducing toxicity by multiple pathways." (PMID 30543710, 2018). "These RNAs may play a role in promoting cancer and inducing toxicity, which are probably involved in arsenic metabolism, just like AS3MT." (PMID 30543710, 2018).
psychiatric disorder (2 papers, 2020 to 2022). A disorder characterized by behavioral and/or psychological abnormalities, often accompanied by physical symptoms. "This is similar to the case with the AS3MT locus, which has shown genome-wide associations with several psychiatric disorders, including affective ones." (PMID 36293479, 2022). "The attention of researchers is mainly attracted to the AS3MT gene that encodes the human enzyme As(III) S-adenosylmethionine methyltransferase catalyzing arsenic biotransformation and is a common risk factor for several psychiatric diseases, including affective disorders and epilepsy." (PMID 36293479, 2022). "Four eGenes (i.e., AS3MT, FLOT1, HLA-A, and PBRM1) are affected by eQTLs from all tested phenotypes and are current therapeutic targets for psychiatric disorders." (PMID 33192679, 2020).
cardiovascular disease (1 paper, 2019). "The top result was AS3MT (p-value = 4.3 × 10−9), related to arsenic metabolism; interestingly, environmental and toxicological studies link arsenic exposure and AS3MT polymorphisms with cardiovascular disease." (PMID 30668570, 2019).
digestive diseases (1 paper, 2021). "Thirty-three interacting genes of AS3MT were further intersected with digestive diseases-associated genes and VPA or OXC-related genes." (PMID 34899152, 2021).
AS3MT also shares sentences with these, for which no sentence is quoted: neurodevelopmental disorder (2 papers); tumor (2); acute promyelocytic leukemia (1); Alzheimer disease (1); attention deficit or hyperactivity disorder (1); hepatocellular carcinoma (1); Hypertension (1); kidney damage (1); ovarian carcinoma (1); polycythemia (1).